CX3CL1 (C-X3-C motif chemokine ligand 1)
Diseases named in the same sentence as CX3CL1 in open-access papers (continued):
Sharing a sentence is not in itself a finding about the gene and the disease.
atrial fibrillation (1 paper, 2016). A disorder characterized by an electrocardiographic finding of a supraventricular arrhythmia characterized by the replacement of consistent P waves by rapid oscillations or fibrillatory waves that vary in size, shape and timing and are accompanied by an irregular ventricular response. "The West Birmingham Atrial Fibrillation Project disclosed in a large cohort of AF patients the independent correlation between low plasma levels of CX3CL1 and low risk of major cardiovascular events." (PMID 27242392, 2016).
B cell lymphomas (1 paper, 2014). "Here we review the different effects of the CX3CL1/CX3CR1 axis in several inflammatory and neurodegenerative diseases and in cancer, with emphasis on human B cell lymphomas." (PMID 24799766, 2014).
bladder cancer (1 paper, 2021). "The expression level of CX3CL1 mRNA in bladder cancer tissues was significantly higher than that in normal tissues (P=0.0268)." (PMID 34671562, 2021). "CX3CL1 was a significant and independent predictor for bladder cancer prognosis." (PMID 34671562, 2021).
brain inflammation (1 paper, 2023). "However, the authors pointed out that the experiments were insufficient to explain either the involvement of BMSC-derived CX3CL1 axis in brain inflammation or which CX3CL1 isoform, between the membrane-bound and the soluble ones, was responsible for reducing Aβ1-42-induced injury in SH-SY5Y cells." (PMID 37175935, 2023).
Burkitt lymphoma (1 paper, 2018). A rare form of malignant mature B-cell non-Hodgkin lymphoma. "CX3CL1 (fractalkine) was shown to recruit macrophages to its source, apoptotic Burkitt lymphoma cells." (PMID 29422896, 2018).
chorioamnionitis (1 paper, 2018). A morphologic finding indicating inflammation of the fetal sac membranes. "CX3CL1 proteins were observed by immunohistochemistry in amnion epithelial cells and trophoblasts obtained from the placenta of patients who suffered from preterm labor arising from chorioamnionitis." (PMID 30399192, 2018).
chronic hepatitis (1 paper, 2015). An active inflammatory process affecting the liver for more than six months. "The expression of CX3CL1 is up-regulated in chronic liver diseases such as chronic hepatitis C16." (PMID 26631623, 2015).
cocaine addiction (1 paper, 2015). "We did not observe main effects of history of cocaine addiction and sex on plasma CX3CL1 concentrations, but there was a significant interaction effect (F1,122 = 4.60, p = 0.034)." (PMID 25762940, 2015).
corneal infection (1 paper, 2024). A viral or bacterial infectious process affecting the cornea. "Individuals with mild corneal infection had significantly higher CX3CL1 concentrations than the control group (P = 0.0049; corrected P = 0.0392)." (PMID 38694515, 2024). "Moreover, the concentration of CX3CL1 was higher in corneal infection patients’ samples than in the control group (P = 0.0017; corrected P = 0.0136)." (PMID 38694515, 2024). "Nevertheless, there wasn’t any statistically significant difference in the concentration of CX3CL1 in the tears of patients with severe corneal infection compared to healthy volunteers or between the severe and mild groups (P = 0.0505) and (P = 0.5201), respectively." (PMID 38694515, 2024).
cyst (1 paper, 2022). A sac-like closed membranous structure that may be empty or contain fluid or amorphous material. "The chemokine profile is different compared to trophozoites, the main up-regulated chemokines are the same, but CCL4, CCL4L2, CSF1, CCL5, CXCL5, and CX3CL1 are more highly up-regulated in the cyst interaction." (PMID 35573800, 2022).
cystic kidney disease (1 paper, 2023). A congenital or acquired kidney disorder characterized by the presence of renal cysts. "Cytokines including CCL2, CSF1 and CX3CL1 are associated with inflammation in cystic kidney diseases." (PMID 36457161, 2023).
cystitis (1 paper, 2008). Inflammation of the urinary bladder. "A similar suggestion has already been made for another chemokine, CX3CL1, and its receptor during CYP-induced cystitis." (PMID 19066630, 2008).
deficiencies (1 paper, 2020). "Given the similar cognitive deficiencies observed in CX3CL1−/− mice in the current study, we next evaluated LTP to determine if these mice display altered synaptic plasticity." (PMID 32410624, 2020).
ductal carcinomas (1 paper, 2007). "In particular, transcription regulators (ATF3, PIGR), genes encoding proteins with cytokine and growth factor activity (PTN, CX3CL1) and genes encoding proteins involved in ion transport and metabolism (ATP1A2, MMP7) were downregulated in ductal carcinomas when compared with normal cells." (PMID 17389037, 2007).
E. coli infection (1 paper, 2026). "Instead, E. coli infection triggered a robust response in the endothelial cells, as evident by elevated levels of IL-6, CCL2, and CX3CL1." (PMID 41408425, 2026).
embryonic carcinoma (1 paper, 2018). "To gain further insight into the regulation of CSF1 and CX3CL1 by miR-125b in embryonic carcinoma, we performed miRNA-Seq of miR-125b antagomir-, miR-125b agomir-, and negative control-transfected NCCIT cells." (PMID 30237497, 2018).
Epiretinal membrane (1 paper, 2020). An epiretinal membrane is a thin sheet of fibrous tissue on the surface of the retina along the inner limiting membrane. "Similarly, a previous study detected very low levels of CX3CL1 in the vitreous fluid of patients with epiretinal membranes and macular holes that were lower than the CXCL16 levels." (PMID 33552057, 2020).
esophageal cancer (1 paper, 2020). A primary or metastatic malignant neoplasm involving the esophagus. "CX3CL1 is highly expressed in esophageal cancer and can promote its metastasis." (PMID 32547955, 2020).
falciparum malaria (1 paper, 2018). "Patients with falciparum malaria also had signs of T-cell subset activation (i.e. increased granzyme B and CX3CL1) and T-cell exhaustion as assessed by high levels of TIM-3 particularly in patients co-infected with HIV." (PMID 30563486, 2018).
Gastric tumors (1 paper, 2020). "Gastric tumors exhibit increased CX3CL1 expression, and CX3CR1 is highly expressed in association with more advanced stages." (PMID 32432034, 2020).
gastritis (1 paper, 2025). Inflammation of the stomach. "In gastritis, CX3CL1 regulates the migration of immune cells (particularly monocytes and macrophages) by binding to the CX3CR1 receptor and helps to direct immune cells toward the site of inflammation, thereby maintaining local immune responses and preventing the spread of pathogens." (PMID 41376630, 2025).
Glomerular sclerosis (1 paper, 2023). Accumulation of scar tissue within the glomerulus. "Herein, we observed that CX3CL1 deficiency reduced cisplatin-induced dysfunction, inflammatory factor aggregation, and glomerulosclerosis in the kidneys of Cis-AKI model mice." (PMID 37875838, 2023).
granulosa cell tumor (1 paper, 2011). A slow-growing, malignant tumor, characterize by the presence of granulosa-like cells and Call-Exner bodies, that is almost always found in the ovary. "CX3CL1 was absent from non-epithelial ovarian granulosa cell tumors." (PMID 21750716, 2011).
Graves disease (1 paper, 2020). Graves' disease is an autoimmune disorder that leads to overactivity of the thyroid gland (hyperthyroidism).It is caused by an abnormal immune system response that causes the thyroid gland to produce too much thyroid hormones. "Also, recently in premenopausal women with nontreated Graves ́ disease, high serum fractaline (chemokine CX3CL1), and lower TBS were found, indicating microarchitectural deterioration linked to increased bone remodeling in these patients." (PMID 32583973, 2020).
head and neck cancer (1 paper, 2020). A primary or metastatic malignant neoplasm affecting the head and neck. "Other significantly elevated cytokines detected in the saliva of head and neck cancer patients included CX3CL1, CCL2, CXCL1 and CCL15, most of which correlated with UWS secretion rates and objective oral dryness (CODS)." (PMID 32911805, 2020).
head and neck squamous cell carcinoma (1 paper, 2023). A squamous cell carcinoma that arises from any of the following anatomic sites: lip and oral cavity, nasal cavity, paranasal sinuses, pharynx, larynx, and salivary glands. "Notably, HPV-positive head and neck squamous cell carcinoma (HNSC) tumor tissues expressed CX3CL1 significantly more than HPV-negative tumor tissues." (PMID 37153002, 2023).
hematoma (1 paper, 2022). A hematoma is a collection of blood from a vascular structure into an extravascular space. "By administrating CX3CL1, it could increase the chemotactic ability of microglia toward the hematoma, accelerate hematoma absorption, and thus improve neurological function recovery." (PMID 36704330, 2022). "You further speculated on the specific mechanism of CX3CL1 promoting hematoma clearance." (PMID 36704330, 2022). "In recent decades, substantial data from ICH have consistently demonstrated that CX3CL1/CX3CR1 signaling can achieve some neuroprotective effects in the pathology of ICH, including contributing to the absorption of hematoma size and reducing cellular death." (PMID 36704330, 2022).
hepatoblastoma (1 paper, 2020). Hepatoblastoma (HB) is a malignant hepatic tumor and is the most common pediatric liver cancer. "The analysis was replicated in two independents cohorts, substantiating that an activation of the CX3CL1/CX3CR1 pathway occurs in hepatoblastomas." (PMID 32432034, 2020). "Overall, we present here novel candidate genes for hepatoblastoma, with evidence that CX3CL1/CX3CR1 chemokine signaling pathway is likely involved with progression, besides reporting specific mutational signatures." (PMID 32432034, 2020). "Altogether, these data suggested that CX3CL1/CX3CR1 upregulation may be a common feature of hepatoblastomas, potentially related to chemotherapy response and progression." (PMID 32432034, 2020).
hepatopulmonary syndrome (1 paper, 2025). Hepatopulmonary syndrome (HPS) is a lung disease characterized by widening of arteries and veins (dilatation) in the lungs in people who have chronic liver disease. "Additionally, interactions between EDNRB and other signaling pathways, such as the C-X3-C motif chemokine ligand 1 (CX3CL1)/C-X3-C motif chemokine receptor 1 (CX3CR1) axis in experimental hepatopulmonary syndrome, underscore the need for caution in therapeutic targeting." (PMID 40597436, 2025).
Hodgkins lymphoma (1 paper, 2023). A heterogeneous group of malignant lymphoid neoplasms of B-cell origin characterized histologically by the presence of Hodgkin and Reed-Sternberg (HRS) cells in the vast majority of cases. "Previous study also showed that the chemotherapy-sensitive Hodgkin lymphoma patients had frequent gains of 16q13, a chromosomal region known to house genes that regulate T-cells trafficking or NF-ĸB activation (CX3CL1, CCL22, CCL17, DOK4, and IL10)." (PMID 37153002, 2023).
hypertriglyceridemia (1 paper, 2023). A laboratory test result indicating elevated triglyceride concentration in the blood. "In HIV-infected patients with hypertriglyceridemia, fenofibrate regulates chemokine gene expression in circulating leukocytes, thereby reducing the expression of C-C motif chemokine receptor 2 (CCR2) and C-X3-C motif chemokine ligand 1 (CX3CL1) to mitigate inflammatory responses." (PMID 36724021, 2023).
influenza infection (1 paper, 2024). "The reduction in or the loss of CX3CL1 during influenza infection may lead to the impairment of both glial regulation and cognitive function." (PMID 38674036, 2024). "Based on the role of CX3CL1/CX3CR1 in influenza, rational immunotherapy is becoming a promising strategy for improving the outcomes of influenza virus infection." (PMID 38674036, 2024). "The chemokines (CCL4, CCL19, CCL10, and CX3CL1) were upregulated in highly pathogenic avian influenza H5N1 (A/duck/India/02CA10/ 2011)-infected lung tissues of chickens, which may be the key factors determining the severity and outcome of influenza infection in chickens." (PMID 38674036, 2024).
ischemia reperfusion injury (1 paper, 2022). Adverse functional, metabolic, or structural changes in ischemic tissues resulting from the restoration of blood flow to the tissue (reperfusion), including swelling; hemorrhage; necrosis; and damage from free radicals. "It was reported that suppression of CX3CL1, a chemo-attractant factor, might be a way for microvesicles to reduce the macrophage infiltration in the ischemia/reperfusion injury kidney." (PMID 36076305, 2022).
knee osteoarthritis (1 paper, 2025). "While an expression correlation analysis of clinical samples has identified CX3CL1 as a potential biomarker for knee osteoarthritis, its receptor CX3CR1 remains unreported in this regard, suggesting a gap that merits further investigation." (PMID 41007174, 2025).
latent infection (1 paper, 2025). "MIs are recruited as CX3CR1+CD8+ T cells by CX3CL1, which is released from inflamed blood vessels, to sites of latent infection and expand on non-hematopoietic cells in IL-15-rich niches." (PMID 40028277, 2025).
leishmaniasis (1 paper, 2019). Infectious disease that is transmitted through the bite of hematophagous female phlebotomine sand flies. "Herein, the inhibition of leishmaniasis-induced activation of astrocytes, microglia, and NFκB reduced spinal cord CX3CL1 mRNA expression as well as Leishmania infection induces CX3CL1 mRNA expression in the ipsilateral DRG of infected mice." (PMID 31138231, 2019). "Leishmaniasis induced significant increase of spinal cord GFAP, Iba-1, TNF-α, IL-1β, CX3CR1, and CX3CL1 mRNA expression, which were inhibited by α-aminoadipate, minocycline, and PDTC treatments (p < 0.05)." (PMID 31138231, 2019).
Lewis lung carcinoma (1 paper, 2025). "A murine model of Lewis lung carcinoma (LLC) cells selected for high CX3CL1 (also known as fractalkine or FKN) expression showed increased NK cell infiltration and decreased tumor growth in bone metastases." (PMID 40849493, 2025).
liver inflammation (1 paper, 2012). "CX3CR1 and CX3CL1/fractalkine have been implicated in the liver fibrosis and their interaction prevents CCl4-induced liver inflammation and fibrosis in the mouse mainly because of the suppression on activation of kupffer cells (KCs) and HSCs." (PMID 22905138, 2012).
lupus erythematosus (1 paper, 2018). An autoimmune, connective tissue chronic inflammatory disorder affecting the skin, joints, kidneys, lungs, heart, and the peripheral blood cells. "For example, soluble CX3CL1 levels are increased in plasma and CSF of patients with lupus erythematosus." (PMID 30245615, 2018).
mastitis (1 paper, 2024). Inflammation of breast tissue during lactation or postpartum due to an obstructed duct or infection. "The results indicated that CX3CL1 may be suggestively relevant to the risk of mastitis (odds ratio, OR = 1.434, 95% CI = 1.142~1.800, p = 0.002)." (PMID 39399489, 2024). "And it was shown that CX3CL1, CD28- CD8dim %CD8dim and CD45 on CD33br HLA DR+ may suggestively be the upstream causes of mastitis, while heightened levels of CD39+ secreting Treg AC were connected to a reduced mastitis risk." (PMID 39399489, 2024).
memory impairment (1 paper, 2023). "The current study investigated the mechanism of the CX3CL1/CX3CR1 signal in memory impairment in mice induced by simulated high-altitude exposure." (PMID 37234914, 2023).
metastatic cancer (1 paper, 2024). A carcinoma which has spread from the original site of growth to another anatomic site. "The signal peptide and chemokine domains of CX3CL1 are the essential components for tumor lymphangiogenesis of aggressive, metastatic cancer." (PMID 38775151, 2024).
Miscarriage (1 paper, 2014). A pregnancy that ends at a stage in which the fetus is incapable of surviving on its own, defined as the spontaneous loss of a fetus before the 22th week of pregnancy. "In conclusion, we have found plasma concentrations of the cytokines IL-1β, IL-6 and IL-10, and the chemokines, CXCL8, CCL2, CCL5, CCL7, CX3CL1 cannot predict subsequent miscarriage." (PMID 24699265, 2014).
monoclonal gammopathies (1 paper, 2019). "We firstly evaluated BM CX3CL1 levels in our cohort of 111 patients, including 16 patients with monoclonal gammopathy of undetermined significance (MGUS), 25 with smoldering myeloma (SMM), and 70 with active MM, and 10 healthy donors (HD) as controls." (PMID 30845779, 2019). "We showed that higher levels of soluble CX3CL1 were present in the BM plasma of MM patients as compared with indolent monoclonal gammopathies." (PMID 30845779, 2019). "In the present study, we analyzed the BM levels of CX3CL1 in a large cohort of patients with MM and indolent monoclonal gammopathies, and we identified the CX3CL1/CX3CR1 axis as a new player of the vascular microenvironment involved in MM-induced angiogenesis." (PMID 30845779, 2019). "In conclusion, our data indicate that BM CX3CL1 plasma levels are increased across the progression of monoclonal gammopathies from MGUS to MM and that the high CX3CL1 BM levels in MM correlated with the presence of a high grade of vascularization." (PMID 30845779, 2019). "Firstly, we analyzed bone marrow (BM) plasma levels of CX3CL1 in 111 patients with plasma cell disorders including 70 with active MM, 25 with smoldering myeloma (SMM), and 16 with monoclonal gammopathy of undetermined significance (MGUS)." (PMID 30845779, 2019). "Our data indicated the CX3CL1 progressively increased across the monoclonal gammopathies and correlated with the BM MVD and PC infiltration but not with the presence of osteolytic bone disease." (PMID 30845779, 2019).
mood disorder (1 paper, 2025). A cognitive disorder a disturbance in which the person's mood is hypothesized to be the main underlying feature. "Dysregulation Dysregulated CX3CL1 expression may contribute to the persistence of mood disorders." (PMID 41155506, 2025).
Myalgia (1 paper, 2023). "Increase in MCP-2 was specifically associated with subjective fever and chills, while CX3CL1 and TNF-α were associated with objective fever and myalgia." (PMID 38235127, 2023).
myeloid leukemia (1 paper, 2023). A clonal proliferation of myeloid cells and their precursors in the bone marrow, peripheral blood, and spleen. "Subsequent secretion of C-X3-C motif chemokine ligand 1 (CX3CL1), a unique chemokine, increased and promoted the migration of the human myeloid leukemia mononuclear (THP-1) cells." (PMID 37035243, 2023).
myositis (1 paper, 2012). "We also found that the treatment of EAM mice with anti-CX3CL1 mAb significantly improved the myositis." (PMID 22394569, 2012). "Our earlier data showed that CX3CL1 and CX3CR1 were expressed in murine EAM and that inhibition of CX3CL1 ameliorated myositis." (PMID 22394569, 2012). "Taken together, these findings suggest that CX3CL1 might play an important role in myositis, and therefore that blockade of CX3CL1 might be therapeutically beneficial for patients with PM and patients with DM." (PMID 22394569, 2012). "Moreover, the CX3CL1 level was significantly associated with the serum CK level and MMT score, which are indicative of myositis." (PMID 22394569, 2012). "Consequently, although CX3CL1 is not a disease-specific marker, upon diagnosis of PM or DM the serum level of CX3CL1 could be a useful marker of disease activity of myositis, as well as for the complicated ILD." (PMID 22394569, 2012). "To determine whether the serum CX3CL1 level could be a biomarker of the disease activities of PM and of DM, we examined the correlation between serum CX3CL1 and serum CK or MMT score, which are thought to be markers of myositis activity." (PMID 22394569, 2012).